GLI3 (GLI family zinc finger 3)
Diseases named in the same sentence as GLI3 in open-access papers (continued):
Sharing a sentence is not in itself a finding about the gene and the disease.
liver cancer (2 papers, 2018 to 2020). An epithelial or non-epithelial malignant neoplasm that arises from the liver. "The correlation of CD90 expression with Gli1 (R = .1442, P = .3128) and Gli3 (R = .2786, P = .0477) was also validated by these expression results in clinical liver cancer tissues." (PMID 29722127, 2018). "These molecular and cellular assays fully validated that the stem cell properties of CD90+ liver cancer cells were mediated by Gli1 and Gli3 expression." (PMID 29722127, 2018). "For further validation of the correlation expression of CD90, Gli1 and Gli3 in liver cancer cells, the expression levels of these 3 genes among 51 pairs of liver cancer tissues and corresponding adjacent normal tissues were analysed by quantitative RT‐PCR." (PMID 29722127, 2018). "More importantly, the expression of Gli1 and Gli3 showed similar expression patterns in these liver cancer cell lines." (PMID 29722127, 2018). "The MTS assay showed that the proliferation rates of CD90+ liver cancer cells transfected with Gli1 or Gli3 siRNA were significantly decreased in comparison with the negative control." (PMID 29722127, 2018). "Our quantitative RT‐PCR and Western blotting experiments showed that the expression of CD90 was also significantly down‐regulated by knockdown of Gli1 and Gli3 expression in CD90+ liver cancer cells." (PMID 29722127, 2018). "We then re‐assessed the expression levels of Gli1 and Gli3 among these cancer tissues with high CD90 expression and observed elevated Gli1 and Gli3 expression in high‐CD90 liver cancer tissues." (PMID 29722127, 2018). "CD90 expression exhibited a high positive correlation with Gli1 and Gli3 in multiple liver cancer cell lines and human cancerous liver tissues, both of which showed a significant increase in liver cancer." (PMID 29722127, 2018). "Since then, research on mouse and human Gli3/GLI3 mostly focused on its role in brain and limb development with certain exceptions of Gli3/GLI3’s role in angiogenesis, colorectal and liver cancer, TRAIL-dependent apoptosis and its role in regulating the IL-6/JAK2 pathway." (PMID 32245491, 2020). "Additionally, the positive correlation of CD90 expression with Gli1 (R = .5347, P < .0001) and Gli3 (R = .4529, P < .0001) was also validated by these expression results in liver cancer tissues." (PMID 29722127, 2018). "Similarly, the transwell assay showed that the migration rates of CD90+ liver cancer cells were remarkably suppressed by transfection with Gli1 and Gli3 siRNAs." (PMID 29722127, 2018). "Moreover, the sphere formation capacity of CD90+ liver cancer stem cells was also greatly inhibited by depletion of Gli1 and Gli3 expression As." (PMID 29722127, 2018). "For a more reliable correlation of CD90, Gli1 and Gli3 expression levels with liver cancer progression, pathological data from the Cancer Genome Atlas (TCGA) containing expression profiles of 365 liver cancer patients were further analysed as described in the Material and Methods section." (PMID 29722127, 2018). "Consistent results were observed in CD90+ liver cancer cells treated with SHH, which were completely reversed compared with those transfected with Gli1 or Gli3 siRNA." (PMID 29722127, 2018). "In contrast, knockdown of Gli1 and Gli3 significantly down‐regulated IL‐6, phosphorylated JAK2, phosphorylated STAT3protein abundances in CD90+ 97L liver cancer cells." (PMID 29722127, 2018). "After siRNA transfection, the expression of Gli1 and Gli3 showed a significant decrease compared with the negative control, demonstrating the efficient knockout of gene expression in liver cancer cells." (PMID 29722127, 2018). "More importantly, the in vivo tumorigenicity assay showed that the sizes and weights of tumours originating from CD90+ liver cancer cells with suppressed Gli1 or Gli3 expression were markedly reduced compared with the negative control." (PMID 29722127, 2018).
liver cancer (continued). "Functional analysis was conducted by siRNA‐mediated CD90, Gli1 and Gli3 gene knockdown, SHH treatment and application of the JAK2 inhibitor AZD1480 and IL6 neutralizing antibody in CD90+ liver cancer stem cells, followed by cell proliferation, migration, sphere formation and tumorigenicity assays." (PMID 29722127, 2018).
Lujan syndrome (2 papers, 2019). "Previous studies have shown that MED12 mutations in FG and Lujan syndromes disrupt a mediator‐imposed constraint on GLI3‐dependent SHH signaling." (PMID 30729724, 2019). "Mutations that cause FG syndrome (p.R961W) and Lujan syndrome (p.N1007S) were found to compromise the mediator‐imposed constraint on GLI3‐dependent SHH signaling and result in increased transcript levels for multiple GLI3 target genes in lymphoblasts from patients." (PMID 30729724, 2019). "The Gli3‐dependent Sonic Hedgehog (SHH) signaling pathway has been implicated in the original FG syndrome and Lujan syndrome." (PMID 30729724, 2019). "Interestingly, in the case of MED12, it was demonstrated experimentally that the substitutions p.Arg961Trp and p.Asn1007Ser (causing FG and Lujan syndromes, respectively), exhibit impaired recruitment of CDK8 onto GLI3-target gene promoters, leading to hyperactivated GLI3-dependent SHH signaling." (PMID 30905399, 2019).
lymph node metastasis (2 papers, 2015 to 2020). "GLI3 encodes a zinc-finger transcription factor that modulates the sonic hedgehog (SHH) pathway, and one recent study on NSCLC demonstrated that overexpression of truncated GLI3 was significantly associated with lymph node metastasis and poor survival." (PMID 26647728, 2015).
metastatic melanoma (2 papers, 2013 to 2026). A melanoma that has spread from its primary site to another anatomic site. "Interestingly, a lower level of GLI3, which predominantly serves as a repressor of Hh pathway target genes, emerged as a distinctive marker for metastatic melanoma compared to cells derived from primary lesions." (PMID 41596411, 2026). "Finally, increased SMO expression and decreased expression of the hedgehog pathway repressor GLI3 correlated with shorter post recurrence survival in metastatic melanoma patients." (PMID 24287465, 2013).
neuroblastoma (2 papers, 2014 to 2021). Neuroblastoma (NB) is the most common solid, extracranial childhood tumor. "GLI2, GLI3 and especially GLI1 knockdown reduced neuroblastoma cell growth compared with siRNA control." (PMID 25134527, 2014).
omphalocele (2 papers, 2011 to 2022). Omphalocele is an embryopathy classified in the group of abdominal celosomias and is characterized by a large hernia of the abdominal wall, centered on the umbilical cord, in which the protruding viscera are protected by a sac. "Another report in murine models described an association between Gli3−/− mutants and omphalocele, whereas left-sided congenital diaphragmatic hernia was observed in Gli3, Gli2 and in a Gli2/Gli3 double mutant." (PMID 35885957, 2022). "We analyzed the lower body wall phenotypes of combinatorial mutantsof Shh, Gli3 and Alx4 genes.We also analyzed conditional gain-of-function mutants of Hh signaling andrevealed the Hh signal dose-dependent pathogenesis of omphalocele and pubicdiastasis phenotypes." (PMID 21283718, 2011). "Moreover, mouse mutants of Sonic hedgehog (Shh), GLI-Kruppel family member 3 (Gli3) and Aristaless-like homeobox 4 (Alx4), members of the hedgehog signaling pathway, were involved in ventral body wall malformation especially in pups with omphalocele phenotypes." (PMID 35885957, 2022).
orofaciodigital syndrome (2 papers, 2019 to 2022). Two syndromes of oral, facial, and digital malformations. "Several diagnostic hypotheses led to the non-conclusive exploration of GLI3 (Pallister-Hall), OFD1 (Orofaciodigital syndrome I) and the known BBS genes at that time (BBS1-BBS18) using Sanger and targeted exome sequencing." (PMID 30761183, 2019).
prostate tumor (2 papers, 2023 to 2025). "GLI3 levels are significantly higher in prostate tumors with SPOP mutations." (PMID 40432836, 2025). "Moreover, GLI3 interacts with AR to enrich AR-dependent gene expression, leading to the castration-resistant growth of prostate tumours." (PMID 38126976, 2023).
renal agenesis (2 papers, 2009 to 2022). Renal agenesis (RA) is a form of renal tract malformation characterized by the complete absence of development of one or both kidneys (unilateral RA or bilateral RA respectively), accompanied by absent ureter(s). "Variants in GLI3 have also been associated with CAKUT or renal agenesis." (PMID 35361250, 2022).
schizophrenia (2 papers, 2014 to 2020). A major psychotic disorder characterized by abnormalities in the perception or expression of reality. "Genetic variation in MED12 which has been implicated in neural development is associated with schizophrenia, and its mutations link with deregulated GLI3-dependent sonic hedgehog signaling pathway." (PMID 25522158, 2014).
syndactyly (2 papers, 2020 to 2025). A disease characterized by the presence of syndactyly, including syndromic and non-syndromic forms. "Our study shows that this novel GLI3 variant contributes to the malformations in this family and provides evidence for the mechanism by which GLI3 c.739C > T (p.Gln247∗) was implicated in the pathogenesis of polydactyly and syndactyly." (PMID 33304378, 2020). "Our study shows that this novel GLI3 variant (GLI3 c.739C > T/p.Gln247∗) contributes to the malformations in a four-generation family with polydactyly and syndactyly and provides evidence for the mechanism by which the GLI3 p.Gln247∗ implicated in the pathogenesis of polydactyly and syndactyly." (PMID 33304378, 2020). "The clinical phenotypes of patients with GLI3 variant-induced limb malformations are complex and varied, including PPD, PAP, syndactyly, and other syndromes." (PMID 41142227, 2025).
acute leukemia (1 paper, 2019). A clonal (malignant) hematopoietic disorder with an acute onset, affecting the bone marrow and the peripheral blood. "In line with our data, GLI3 was demonstrated to be epigenetically silenced in patients with acute leukemia." (PMID 31109375, 2019).
adenoma (1 paper, 2024). A neoplasm arising from the epithelium. "In patient samples, adenoma patients exhibited increased expression of genes associated with the tumor immune microenvironment, such as IL6ST, collagen family members, and CRC transition markers, such as GLI3 and PIEZO2, in CARD11+ adenoma patients." (PMID 39408697, 2024). "For the validation of some key genes identified in adenoma (IL6ST, GLI3) and carcinoma (MAPK8IP2, CPEB4) patients, survival analysis was completed by using the Kaplan–Meier Plotter." (PMID 39408697, 2024).
adrenal aplasia (1 paper, 2022). "Mouse bearing a similar Gli3 allele was also first reported to have adrenal aplasia but a subsequent study using the same model did not observe this phenotype." (PMID 36430866, 2022). "It was originally suggested that GLI3 might have a role in adrenal development, as the expression of a truncated GLI3 with constitutive transcriptional repressor activity leads to the development of Pallister–Hall syndrome in human, which also included adrenal hypoplasia or aplasia in some cases." (PMID 36430866, 2022).
ameloblastoma (1 paper, 2013). The most common odontogenic tumor, arising from the epithelial component of the embryonic tooth and usually affecting the molar-ramus region of the mandible or maxilla. "We detected expression of SHH, patched, GLI1, GLI2 and GLI3 in the ameloblastoma specimens and AM-1 cells." (PMID 23835807, 2013). "In the present study, we examined the expression of SHH, PTCH, GLI1, GLI2, and GLI3 in ameloblastoma and investigated their functions using an ameloblastoma cell line." (PMID 23835807, 2013). "In ameloblastoma, immunoreactivity for SHH, PTCH, GLI1, GLI2 and GLI3 was seen in almost all tumor cells, but not in the stromal cells." (PMID 23835807, 2013).
anaplastic large cell lymphoma (1 paper, 2021). Anaplastic large cell lymphoma (ALCL) is a rare and aggressive peripheral T-cell non-Hodgkin lymphoma, belonging to the group of CD30-positive lymphoproliferative disorders, which affects lymph nodes and extranodal sites. "Investigation of the expression of FDC markers in HL and anaplastic large cell lymphoma (ALCL) revealed GLI3, fascin (actin-bundling protein found in membrane ruffles), and TUBB3 (a member of the beta-tubulin protein family) as the most sensitive markers, which were diffusely positive in HL." (PMID 33494284, 2021).
Anxiety (1 paper, 2026). Intense feelings of nervousness, tension, or panic often arise in response to interpersonal stresses. "Female double heterozygote Gli2+/-; Gli3+/699 mice showed reduced social behavior and increased anxiety-like behaviors." (PMID 42219751, 2026).
asthma (1 paper, 2025). "Experimental studies have shown that Smo and GLI3 are upregulated during in vitro Th17 polarisation and in vivo models of Th17-dominant asthma." (PMID 41573715, 2025).
Atrophy (1 paper, 2023). Any weakening or degeneration, especially through lack of use. "In case 1, MRI confirmed atrophy of the right hemisphere, which, to our knowledge, has not been associated with PHS; therefore, it is unclear whether this feature is related to the mosaic GLI3 variant identified in this individual." (PMID 39669239, 2023).
Autoimmunity (1 paper, 2018). The occurrence of an immune reaction against the organism's own cells or tissues. "It will also be important to investigate the influence of Gli3 on shaping the TCR repertoire and in autoimmunity." (PMID 29361554, 2018).
bone tumors (1 paper, 2024). "In tumor cell lines, bone tumors displayed the highest expression of both GLI1 and GLI2, whereas skin tumor cell lines exhibited the greatest expression of GLI3." (PMID 38498906, 2024).
brachydactyly (1 paper, 2025). A disease characterized by the presence of brachydactyly, including syndromic and non-syndromic forms. "The pathway's therapeutic vulnerability emerges through SPOP‐GLI3 regulatory axis manipulation, where SPOP depletion‐induced osteopenia and brachydactyly are rescued by GLI3 repressor attenuation." (PMID 40857061, 2025).
brain malformation (1 paper, 2025). "The GLI3 variant in our patient explains the cephalopolysyndactyly phenotype but not necessarily the epileptogenic brain malformation." (PMID 39859528, 2025).
Cerebellar dysplasia (1 paper, 2024). Cerebellar dysplasia (abnormal growth or development) is defined by abnormal cerebellar foliation, white matter arborization, and gray-white matter junction. "Loss of SHH pathway inhibition in neural stem cells and GCs from lack of GPR161 and SUFU, which promotes cleavage of GLI3 into the transcriptional repressor GLI3R, can lead to hyperproliferation and cerebellar dysplasia." (PMID 39137043, 2024).
choriocarcinoma (1 paper, 2014). An aggressive malignant tumor arising from trophoblastic cells. "Downregulation of Gli1, Gli2, Gli3 and Kif7 was demonstrated in clinical samples of choriocarcinoma and hydatidiform moles as well as choriocarcinoma cell lines when compared with normal placentas." (PMID 25265279, 2014).
colorectal adenoma (1 paper, 2024). An adenoma that arises from the colon or rectum. "Genes related to CARD11 overexpression in colorectal adenoma patients included IL6ST, GLI3, and PIEZO2, as well as the collagen-related gene family, whilst MAPK8IP2 gene expression was dramatically elevated in CARD11+ carcinoma patients." (PMID 39408697, 2024).
Coma (1 paper, 2021). The complete absence of wakefulness and consciousness, which is evident through a lack of response to any form of external stimuli. "Interestingly, we observed a significant increase in the general activity in COMA patient–derived fibroblasts compared with control cells resulting in higher basal expression levels of GLI1, GLI2, GLI3, and PTCH1." (PMID 33024317, 2021).
corpus callosum agenesis (1 paper, 2021). "Patients with postaxial phenotypes have a higher risk of having a truncating variant in the activator domain of the GLI3 gene which is also related to a higher risk of corpus callosum agenesis." (PMID 32591344, 2021). "Thus, we advocate to differentiate preaxial or postaxial oriented GLI3 phenotypes to explain the pathophysiology as well as to get a risk assessment for corpus callosum agenesis." (PMID 32591344, 2021). "The higher risk of corpus callosum agenesis in this population shows that differentiating between a preaxial phenotype and a postaxial phenotype, instead of between the different GLI3-mediated polydactyly syndromes, might be more relevant regarding diagnostics for corpus callosum agenesis." (PMID 32591344, 2021).
Crohn disease (1 paper, 2022). A gastrointestinal disorder characterized by chronic inflammation involving all layers of the intestinal wall, noncaseating granulomas affecting the intestinal wall and regional lymph nodes, and transmural fibrosis. "High levels of IL-6 were reported in Castleman’s and Crohn’s disease as well as in RA patients, suggesting GLI3 may play a role in these diseases." (PMID 35937499, 2022). "Additionally, increased expression of TLR3 and TLR4 was reported in RA patients and TLR4 was upregulated in Crohn’s disease, suggesting GLI3 may regulate the pathology of Crohn’s disease and RA through modulation of IL-6." (PMID 35937499, 2022).
cyst (1 paper, 2025). A sac-like closed membranous structure that may be empty or contain fluid or amorphous material. "The upregulation of Gli3 transcript between P10 and P14 is in line with the period of rapid cyst progression observed in this model." (PMID 39823139, 2025). "Elevation of Gli3 transcript was in line with the period of rapid cyst progression at the later stages of the disease at P14 to P21." (PMID 39823139, 2025). "Reduction of increased Gli3 levels via heterozygous genetic deletion in Cpk mice did not affect cyst formation." (PMID 39823139, 2025). "Conversely, in a Pkd1‐mutant mouse, the genetic overactivation or deletion of Smo, or deletion of both Gli2 and Gli3, specifically in renal epithelial cells did not alter cyst formation." (PMID 39823139, 2025). "Overall, we have demonstrated that although levels of GLI3 are enhanced in models of ARPKD, dampening this upregulation does not alter cyst progression or spheroid size in mouse and human models respectively, highlighting the functional complexity of the Hh pathway in ARPKD." (PMID 39823139, 2025).
cystic kidneys (1 paper, 2025). "Additionally, a shift toward the processing of GLI3 full length activator protein to the truncated repressive form is observed in cystic kidneys in the Cpk model of ARPKD." (PMID 39823139, 2025).
deafness (1 paper, 2022). An inherited or acquired condition characterized by the complete loss of the ability to hear from one or both ears. "Twenty-four genes were present in both normal hearing high variant load lists, including three deafness genes (POLG, GLI3, MYO3A)." (PMID 35761239, 2022).
endothelial dysfunction (1 paper, 2025). In vascular diseases, endothelial dysfunction is a systemic pathological state of the endothelium (the inner lining of blood vessels) and can be broadly defined as an imbalance between vasodilating and vasoconstricting substances produced by (or acting on) the endothelium. "This study demonstrates that histone lactylation-mediated GLI3 activation drives macrophage M1 polarization and subsequent secretion of exosomal SERPINE1, inducing endothelial dysfunction in AAA progression." (PMID 41213933, 2025).
Esophageal atresia (1 paper, 2013). A developmental defect resulting in complete obliteration of the lumen of the esophagus such that the esophagus ends in a blind pouch rather than connecting to the stomach. "Gli2–/–,Gli3+/– mutants displayed esophageal atresia with tracheo-esophageal fistula and a severe lung phenotype." (PMID 24274029, 2013).